IL1B (interleukin 1 beta)
Diseases named in the same sentence as IL1B in open-access papers (continued):
Sharing a sentence is not in itself a finding about the gene and the disease.
gram-negative bacterial infections (12 papers, 2017 to 2025). Infections caused by bacteria that show up as pink (negative) when treated by the gram-staining method. "The results of the initial Wilcoxon rank sum tests provided evidence of immunomodulation by SCFP in relation to IL-1β pathways associated with Gram-negative bacterial infection." (PMID 39595313, 2024). "For Gram-negative bacterial infections, this response is elicited through a lipopolysaccharide (LPS)-induced-peripheral IL-1β release which in turn stimulates the release of brain-endogenous cytokines that act on hypothalamic appetite control." (PMID 34352037, 2021). "IL-1β contributes to macrophage recruitment, Streptococcus pneumoniae clearance, and the protection of mice from lethal Gram-negative bacterial infection." (PMID 34437417, 2021). "A recent report documented that TLR4-TRIF signaling and the IRF-3-mediated type I IFN response play important roles for in vivo IL-1β processing and production in response to Gram-negative bacterial infection." (PMID 32373120, 2020). "In particular, SNP rs2237499 affected IL-1β levels upon LPS (Gram-negative bacterial infection), whereas SNP rs13380717 altered IFN-γ levels in response to C. albicans hyphae infection." (PMID 31475010, 2019). "In the non-canonical NLRP3 inflammasome pathway, IL-1β induction in mice and humans after Gram-negative bacterial infections required interferon (IFN)-inducible caspase-11 in mice, or caspase-4/5 in humans." (PMID 32373120, 2020). "Type I IFN is necessary for IL-1β production by the non-canonical NLRP3 inflammasome in response to Gram-negative bacterial infection." (PMID 32373120, 2020).
Heat Stroke (12 papers, 2010 to 2024). A condition caused by the failure of body to dissipate heat in an excessively hot environment or during PHYSICAL EXERTION in a hot environment. "The use of Nlrp3 knockout mice enhanced heat tolerance and alleviated heat stroke-induced death by reducing mice hypothalamus IL-1β production with prior infection condition." (PMID 34092247, 2021). "When infection and heat stroke occurred simultaneously or in short succession, IL-1β was extensively produced." (PMID 34092247, 2021). "The plasma levels of pro-inflammatory cytokines such as TNF-α and IL-1β are elevated following heat stroke." (PMID 29416747, 2018). "Both CD34− PDMSCs and CD34+ HUCB equally attenuated heat stroke-induced overexpression of both IL-1β and TNF-α in rats." (PMID 29416747, 2018). "The immediate treatment with HES alone and the combined agent at the onset of heat stroke attenuated the heat stroke-induced increased serum lipid peroxidation, as well as attenuating it increased the serum levels of IL-1β and TNF-α." (PMID 20937119, 2010). "The previous studies had also shown that heat stroke induced systemic and cerebral striatal productions of IL-1β and TNF-α in both rats and rabbits." (PMID 20937119, 2010). "Previous studies have demonstrated that SMS treatment could ameliorate cerebral iNOS reactivity and NO production, and reduce serum levels of TNFα, IL-1β, and IL-6 in heat stroke rats." (PMID 39156108, 2024). "Our hypothesis proposes the involvement of Kupffer cell ferroptosis during heat stroke, initiating IL-1β-mediated inflammation." (PMID 39309491, 2024). "Studies have shown that the mortality of heat stroke was closely related to the level of IL-1β." (PMID 34092247, 2021). "In addition, IL-1β neutralizing antibody was injected to test potential therapeutic effect on heat stroke." (PMID 34092247, 2021). "Furthermore, IL-1β neutralizing antibody injection significantly extended endotoxemic mice survival under heat stroke." (PMID 34092247, 2021). "A significant increase was detected in IL-1β levels in the serum of EHS or CHS mice at the onset of heat stroke; furthermore, its levels peaked at 6 h, indicating that acute inflammation may occur during the early stages of heat stroke." (PMID 32655408, 2020). "Both cell populations could improve outcomes following heat stroke by preventing the overproduction of pro-inflammatory cytokines including IL-1β and TNF-α." (PMID 29416747, 2018). "Furthermore, the present results show that treatment with the combined agent significantly attenuates the heat stroke-induced overproduction of IL-1β and TNF-α in the serum." (PMID 20937119, 2010). "Our results indicated that following heat stroke, arterial hypotension, decreased cerebral blood flow, increased serum levels of IL-1β, TNF-α and MDA, and increased striatal dopamine, serotonin and hydroxyl radicals and increased of levels of glutamate, glycerol and lactate/pyruvate ratio developed." (PMID 20937119, 2010). "IL-1β may serve as a biomarker for heat stroke severity and potential therapeutic method." (PMID 34092247, 2021). "Our previous results revealed that systemic pretreatment with exogenous GCs, such as DXM, before exposure to heat stress, but not immediate treatment at onset of heat stroke, could increase the survival time via reduction of serum interleukin-1β (IL-1β) in rat heat stroke." (PMID 25411796, 2014). "Concentrations of the ischemic and damage markers, dopamine, serotonin, and hydroxyl radical productions in corpus striatum, and the serum levels of interleukin-1 beta, tumor necrosis factor-alpha and malondialdehyde (MDA) were observed during heat stroke." (PMID 20937119, 2010). "The serum concentrations of inflammatory cytokines (such as IL-1β and TNF-α) are elevated in humans and animals with heat stroke." (PMID 20937119, 2010).
Heat Stroke (continued). "Activated inflammation is evidenced by overproduction of pro-inflammatory cytokines (e.g., interleukin-1β (IL-1β) and tumor necrosis factor-α (TNF-α)) in circulation of heat stroke rats." (PMID 20937119, 2010). "Pro-inflammatory cytokines including IL-1β, IL-6, and TNF-α are elevated in both infection and heat stroke, suggesting infection might prime a latent immune response that is synergistically driven by heat challenge and promoted severe pathology." (PMID 34092247, 2021). "Indeed, as it is shown in the present results, an increase of serum IL-1β and TNF-α levels is observed in heat stroke rats." (PMID 20937119, 2010). "The immediate administration of this combined agent might exert its protective effects by attenuating the increased plasma level of IL-1β and TNF-α during heat stroke." (PMID 20937119, 2010). "Then, the hypothesis was confirmed by showing that either LPS or heat stroke alone failed to induce significant caspase-1 p10 or IL-1β maturation." (PMID 34092247, 2021). "Furthermore, we also attempt to ascertain whether the neuroprotective effects of the combined agent treatment are associated with inhibition of cerebral release of glutamate, DA, 5-HT, hydroxyl radicals, and the serum IL-1β, TNF-α and malondialdehyde (MDA) levels during heat stroke." (PMID 20937119, 2010).
hypercoagulability (12 papers, 2014 to 2025). "IL-1β, a known procoagulant, causes induction of tissue factor with increasing vascular endothelial permeability loss ensuing in hypercoagulability-one of the cardinal features of the disease." (PMID 35431536, 2022). "The actors of this cytotoxic effect could be local peritoneal cytokines: previous studies demonstrated that IL-1β and IL-6 induce structural and morphological changes in RBCs, eryptosis, and hypercoagulability." (PMID 38673869, 2024).
hypoxic-ischemic encephalopathy (12 papers, 2014 to 2025). "Higher cerebrospinal fluid IL-1b, IL-23 and IL-33 concentrations at pre-cesarean time were significantly associated with increased odds of perinatal depression." (PMID 38820411, 2024). "We, in a former study, have reported sensitivity and specificity of 80.5% and 81.6%, respectively, for IL-6; and 71% and 89.1%, respectively, for IL-1β, in diagnosis of perinatal asphyxia." (PMID 33680378, 2020). "Combination of IL6 and IL-1β at birth was studied in 38 infectious infantswith perinatal asphyxia (pH < 7.2, low Apgar score, and fetal distresssymptoms) and 47 healthy infants." (PMID 31435616, 2019). "IL6 and IL-1β of serum samples were used in the earlydiagnosis of perinatal asphyxia and are useful predictors for the outcomes ofperinatal asphyxia and its intensity." (PMID 31435616, 2019). "TNF-α and IL-1β showed prolonged, higher expression levels than the controls, suggesting that the LPS/Hypoxia animals are experiencing a longer inflammatory state similar to that seen in human preterm hypoxic-ischemic encephalopathy." (PMID 40810121, 2025). "IL-1β serum is predictors of term neurologicalconsequences and intensity of perinatal asphyxia." (PMID 31435616, 2019). "Therefore,combination of IL6 and IL-1β can be used as a potential substantially powerfulmarker for early diagnosis of perinatal asphyxia." (PMID 31435616, 2019). "Indeed, a study of blood and CSF obtained during the first 24 h of life from infants who suffered hypoxic ischemic encephalopathy showed an increase in IL-1β, IL-6, and TNF-α levels, compared to control infants." (PMID 24723845, 2014). "A pilot study reported an inverse connection between IL-1β, TNF-α, and IL-17 and perinatal depression." (PMID 37239199, 2023). "IL-1β and IL6 levels have been reported to besignificantly higher in infants with perinatal asphyxia compared to the controlgroup in 24 hr after birth." (PMID 31435616, 2019). "A relationship between serum levels of IL-1β, IL-6, and TNF-α and the outcome of infants that have suffered of perinatal asphyxia has been observed in humans, suggesting that proinflammatory cytokines have a predictive value." (PMID 24723845, 2014). "The turning points forIL6 and IL-1β were 11.91 pb/ml and 3.35 pb/ml, respectively.The researchers concluded that simultaneous assessment of IL6 andIL-1β can improve the sensitivity and specificity forearly diagnosis of perinatal asphyxia." (PMID 31435616, 2019). "Following hypoxic ischemic encephalopathy, ICV injection of human umbilical cord-derived MSCs could exhibit neuroprotective effects via suppressing apoptosis and regulating the secretion of TNF-α and IL-1β." (PMID 37605722, 2023).
ileitis (12 papers, 2019 to 2024). "Previous studies conducted by the authors have also demonstrated that supplementation with acrylamide results in local ileitis with such symptoms as the increased synthesis of proinflammatory cytokines by gut-associated lymphoid tissue (GALT) (Interleukin 1β (IL-1β), IL-6, TNF-α)." (PMID 32225044, 2020). "GLP-2 treatment reduced levels of pro-inflammatorycytokines (IFN-γ, TNF-α, and IL-1β) and induciblenitric oxide synthase, with increased levels of IL-10 in ileitis andcolitis models." (PMID 37491005, 2023). "A recent study revealed the critical role of B. intestinalis and IL-1β signaling in immune checkpoint blockade (ICB) therapy-induced ileitis." (PMID 37834058, 2023). "IL-1β and IL-1 signaling can induce ileitis during acute infection through peroral infection and cachexia during chronic infection in mice." (PMID 35626667, 2022). "Moreover, gene expression of several sensors, as well as downstream effectors including IL-1β, also correlated to the disease activity for CD patients with ileitis." (PMID 35190924, 2022). "This ileitis is due to the strong T-helper 1 biased immune response, characterized by the overproduction of pro-inflammatory mediators including; IFN-γ, TNFα, IL1β, IL18, and NO, commonly known as “cytokine storm”." (PMID 38743178, 2024). "As T. gondii-induced ileitis upregulated inflammasome mRNA, we measured the protein expression levels of NLRP3 and IL-1β in the ileal tissue." (PMID 36831091, 2023).
irritable bowel syndrome (12 papers, 2016 to 2025). Irritable bowel syndrome (IBS) is a chronic functional condition of the lower gastrointestinal (GI) tract characterized by abdominal pain or discomfort and disordered bowel habit (diarrhea, constipation, or fluctuation between the two). "Moreover, IL-1β also appears to promote BDNF release in enteric glial cells in subjects with irritable bowel syndrome; and levels of this cytokine have also been correlated with the severity and frequency of abdominal pain in this context." (PMID 34638711, 2021). "And compared to control rats and enteric glial cells, the expression levels of GFAP, S100B, SP, CGRP, TRPV1, TNF, IL-1β, and IL-6, were significantly higher in the colonic tissues of irritable bowel syndrome (IBS) rats and lipopolysaccharide (LPS)-treated EGCs." (PMID 40225339, 2025). "In the irritable bowel syndrome (IBS) model, EA at ST36 has been found to decrease the level of mast cells (MC) and downregulate interleukin-1β (IL-1β) in colon tissue, thus improving visceral hypersensitivity." (PMID 38274501, 2023). "SP stimulates the synthesis of TNF-α, IL-1β, and IL-6 in the human colonic mucosa, increases the production of IL-1β and IL-6 mRNA in human glial cells, and co-operates with mast cells in the wall of ileum and ascending colon of irritable bowel syndrome (IBS) patients." (PMID 33353157, 2020).
myositis (12 papers, 2008 to 2025). "Importantly, these interactive cellular networks culminate in a TH1 driven, pro-inflammatory cascade (marked by upregulation of genes encoding the TH1-associated cytokines IFNγ, TNFα, and IL-1β) that steers the disease process away from fibrosis and defines the myositis phenotype in WT mice." (PMID 37809058, 2023). "Further understanding of the molecular mechanisms of IL-1β in the pathogenesis of myositis is required." (PMID 35965334, 2022). "An in vitro study on primary human muscle cell cultures from myositis patients showed that immunoproteasome is involved in the maintenance of myokines (IL-6, IL-1β, CXCL9, and CXCL10) production and in MHC I overexpression." (PMID 32775472, 2020). "Immune infiltrates with Th17 cells are seen in myositis and a previous paper from the laboratory showed that IL-17 acts on myoblasts to increase the effects of IL-1β." (PMID 31396230, 2019). "The most predominantly reported cytokines in myositis include pro-inflammatory cytokines such as IL-1α, IL-1β, TNF-α and transforming growth factor (TGF)-β." (PMID 23758833, 2013). "When we analyzed the cytokines behavior according to the myositis core set measures, we observed an association with CCL2 and IL-1β, showing higher serum levels when the MYOACT score is equal to zero, which might be interpreted as clinical remission." (PMID 39456842, 2024). "Cultured human myoblasts from patients with myositis constitutively produce a low level of cytoplasmic and secreted IL-15, which was also observed in healthy controls; however, mRNA and protein production was increased in DM patients by stimulation with IL-1α, IL-1β, TNF-α, or IFN-γ." (PMID 30766892, 2019). "We found higher serum levels of IL-10, IL-6, CXCL8, IL-1β, IL-33, IFN-γ, TNF-α, IL-23, and IL-17A in myositis patients compared to the HSs." (PMID 39456842, 2024). "There were limitations to this study due to the short time period of IL-1β and IFNγ exposure considering the progressive, chronic nature of myositis conditions, as well as a lack of investigation of different IL-1β and IFNγ concentrations." (PMID 37731843, 2023). "Expression of IL-1β and TNF-α was detected in perivascular infiltrating macrophages and microglia in the spinal cords of patients with HAM/TSP and in infiltrating macrophage in the muscle of patients with HTLV-I-related myositis." (PMID 22335964, 2012).
Osteopenia (12 papers, 2009 to 2025). Osteopenia is a term to define bone density that is not normal but also not as low as osteoporosis. "Although the reason remains unknown, IL-1β has been known to be involved in the pathogenesis of osteopenia induced by both estrogen deficiency and OA." (PMID 28893232, 2017). "IL-1β induces bone resorption, which is related to subchondral osteopenia in OA." (PMID 28893232, 2017). "Disuse osteopenia, periprosthetic and infection related bone loss are all associated with increases in 'pathological' osteoblast apoptosis, enhanced cell suicide mediated by proinflammatory cytokines such as TNF alpha, anti CD 95-IgM, Il-1β and Il-6." (PMID 19527527, 2009). "Since IL-1β has been shown to mediate the effects of estrogen deficiency on bone, we hypothesized that the NLRP3 inflammasome, via maturation of IL-1β plays a role in estrogen-dependent osteopenia." (PMID 28747793, 2017). "IL-1β is known to be a potent stimulator of bone resorption and has been shown to synergize with PTH in promoting osteopenia in fetal rat long-bone cultures, even when both are used at very low concentrations." (PMID 41341029, 2025). "Salvianolate treatment could increase Osterix, OPN, Runx2 level and decrease TNF-α, IL-6 level in serum and IL-1β protein in TNF-α-induced MC3T3-E1 osteoblasts, finally ameliorate osteopenia and improved bone quality." (PMID 36387862, 2022).
sickle cell disease (12 papers, 2013 to 2025). Sickle cell anemias are chronic hemolytic diseases that may induce three types of acute accidents: severe anemia, severe bacterial infections, and ischemic vasoocclusive accidents (VOA) caused by sickle-shaped red blood cells obstructing small blood vessels and capillaries. "A vicious cycle in sickle cell disease (SCD) involves platelets containing more inflammation-promoting IL-1β, with bacterial exposure increasing IL-1β packaging within EVs." (PMID 39200314, 2024). "It is well-known that hydroxycarbamide (hydroxyurea), a cytoredutor drug indicated for MPN treatment, is capable of lowering serum inflammatory markers such as TNF-α, IL-6, CXCL8, and IL-1β in sickle cell disease patients." (PMID 34084749, 2021). "Plasma concentrations of the pro-inflammatory cytokines TNF-α and IL-1β, the adhesion molecule sICAM-1 and the anti-inflammatory cytokine IL-10 were measured in a total of 55 adult subjects with sickle cell disease and 17 haemoglobin AA controls." (PMID 23922670, 2013). "It was also demonstrated that zinc as an antioxidant could reduce the levels of oxidative stress biomarkers and inflammatory cytokines such as TNF-α and IL-1β in patients with sickle cell disease." (PMID 30127816, 2018). "Compared to a group of healthy controls, sickle cell disease patients had lower plasma zinc, increases in markers of oxidative stress, elevated VCAM-1, increased production of TNF-α and IL-1β, and decreased IFN-γ production at baseline." (PMID 34239993, 2021). "Moreover, monocytes are activated in sickle cell disease with expression of tumour necrosis factor alpha (TNF-α) and interleukin-1 beta (IL-1β) as well as adhesion of molecule ligand, CD11b." (PMID 33238928, 2020). "The involvement of the pro-inflammatory cytokines IL-1β and TNF-α in promoting endothelial adhesiveness, leukocyte activation and the coagulation cascade could render them potent mediators of episodic vasoocclusion in sickle cell disease and in promoting chronic leg ulcers." (PMID 23922670, 2013). "Furthermore, consistent with previous reports suggesting an up-regulation of inflammatory pathways in sickle cell disease vs. controls, we found significantly greater concentrations of the inflammatory cytokine TNF-α, but not IL-1β or the adhesion molecule, ICAM-1 in the sickle cell disease group." (PMID 23922670, 2013).